NEAT1 (nuclear paraspeckle assembly transcript 1)
Diseases named in the same sentence as NEAT1 in open-access papers (continued):
Sharing a sentence is not in itself a finding about the gene and the disease.
cancer (continued). "miR-3158-5p was negatively associated and RAB3B was positively associated with cancer stage, while NEAT1 was positively associated with cancer stage, but without statistical significance (–G)." (PMID 35664777, 2022). "The deregulated NEAT1 RNA metabolism of cancer cells, in turn, may alter gene expression in tumours at various levels: in the context of paraspeckles, on chromatin and in the cytoplasm." (PMID 35457249, 2022). "Many studies have revealed critical roles of Lnc-NEAT1 in a variety of cancers." (PMID 35012431, 2022). "Recent studies revealed that NEAT1 has a significant role in developing different cancer types." (PMID 35581633, 2022). "Upregulation of NEAT1 intensified cancer growth by regulating miR-205-5p." (PMID 35676702, 2022). "LncRNAs may serve as biomarkers of cancer, such as nuclear enriched abundant transcript 1 (NEAT1), HOX Transcript Antisense RNA (HOTAIR), metastasis-associated lung adenocarcinoma transcript 1 (MALAT-1), H19." (PMID 36034367, 2022). "As an endogenous competing RNA (ceRNA), NEAT1 can facilitate the progression of many cancers." (PMID 36011001, 2022). "In addition to the role of lncRNA NEAT1 in cancer, silencing of NEAT1 can also inhibit neuropathic pain and neuroinflammation." (PMID 36466810, 2022). "Indeed, in MDA-MB-231 (TNBC) and MCF7 (ER+/PR+) cancer cell lines NEAT1 by sponging miR-107, upregulates CPT1A expression." (PMID 36182907, 2022). "In contrast, neither rapamycin nor NEAT1_2 significantly affected HCC growth under low glucose conditions, albeit the overall growth rate was also lower due to limited nutrition, suggesting that mTORC1-NEAT1 axis promotes rapamycin-sensitive cancer cell growth through glucose metabolism." (PMID 35547764, 2022). "Moreover, integrated phosphoproteomic and transcriptomic analysis of Cancer Cell Line Encyclopedia (CCLE) datasets showed that p-S6 was negatively correlated with NEAT1 expression." (PMID 35547764, 2022). "The long noncoding RNA NEAT1 is known to be heavily dysregulated in many cancers." (PMID 36139550, 2022). "This lncRNA is considered as a potential biomarker in several cancer types and developing NEAT1-targeting therapies might be a novel strategy against CRC." (PMID 35676702, 2022). "Considering Akt activation in CRC progression, NEAT1 affected the proliferation and apoptosis of CRC via modulation of the Akt pathway and the NEAT1/Akt pathway may act as a possible target for cancer therapy." (PMID 35676702, 2022). "Taken together, NEAT1 functioned as a cancer promoter by regulating miR-524-5p/ID1 axis in PTC." (PMID 35635748, 2022). "NEAT1 has been reported to positively correlate with various cancers." (PMID 36050752, 2022). "Also, NEAT1 and POUF51 genes followed the same trend as NANOG in the MVA, indicating that the pluripotency increasing capacity of the cancer microenvironments was associated with genuine cancer aggressiveness and disease recurrences in the patients." (PMID 35565301, 2022). "Moreover, the expression of NEAT1 is higher in cancer tissues compared with the normal adjacent tissues." (PMID 36011001, 2022). "NEAT1 is a crucial oncogene in cancer and has a big impact on BC’s ability to induce EMT." (PMID 36212140, 2022). "LncRNA-NEAT1 (long non-coding RNA nuclear paraspeckle assembly transcript 1), which is frequently overexpressed in diverse human tumors, is correlated with worse prognosis and survival rates of cancer patients." (PMID 35313796, 2022). "In summary, these results suggest that the high expression of lncRNA NEAT1 tal cancer." (PMID 36213831, 2022). "First, we illustrate the structure and functions of NEAT1 in cancer." (PMID 36011001, 2022). "NEAT1 can also be secreted from other cells and be delivered to cancer cells through exosomes." (PMID 36011001, 2022). "To date, lncRNA NEAT1 has been reported to be aberrantly expressed in different types of cancers." (PMID 34512157, 2021). "NEAT1 promotes distant metastasis and tumor growth in cancer." (PMID 34414852, 2021).
cancer (continued). "NEAT1 is an important oncogene in cancer and significantly affects EMT induction in BC." (PMID 33807045, 2021). "Accumulating evidence have demonstrated that NEAT1 functions as an oncogene in diverse cancers." (PMID 33645623, 2021). "There were also changes in EMT marker levels following NEAT1 knockout in various cancer cell lines." (PMID 33807045, 2021). "Besides the oncogenic role of NEAT1 in cancer biology, it also participates in multiple inflammatory diseases." (PMID 34972503, 2021). "They found that knockdown of NEAT1 could sensitize cancer cells to radiation or chemical drugs through NEAT1-mediated ceRNA networks." (PMID 34512157, 2021). "NEAT1 was reported to serve as a “sponge” of miR-101 to promote the progression and radio-resistance of some types of cancer, including non-small cell lung cancer, hepatocellular carcinoma, papillary thyroid carcinoma, breast cancer and nasopharyngeal carcinoma 25-29." (PMID 34405022, 2021). "Besides cancers, NEAT1 also participates in other physiological and pathological processes, such as inflammatory response, which contributes to RAS." (PMID 34972503, 2021). "In the development of different cancers, NEAT1 has been observed to function as a ceRNA." (PMID 33738254, 2021). "Moreover, NEAT1 has been found to be correlated with poor survival in patients with various cancers." (PMID 33393590, 2021). "NEAT1, serving as a significant cancer‐related lncRNA, can lead to several serious cancers." (PMID 33393590, 2021). "LncRNA NEAT1 functions as an oncogene in multiple human cancers." (PMID 32983133, 2020). "LncRNA NEAT1 is found to act as an oncogene in the majority of human cancers, including GBM." (PMID 32443824, 2020). "Finally, we rediscovered NEAT1 and other long noncoding RNAs (LncRNAs) that are important in the cancer biology as well as in GBM cell growth and invasion." (PMID 33317554, 2020). "Other replication studies could causally link mutations affecting lncRNAs, such as RMRP, NEAT1, or LINC-PINT, to cancer." (PMID 33329688, 2020). "And the mRNA levels of NEAT1 in multiple types of cancer cells were sought by CCLE database." (PMID 33680941, 2020). "NEAT1 is abnormally expressed in a wide variety of human cancers." (PMID 31992741, 2020). "This suggests that NEAT1 expression might either protect or enhance cancer initiation and progression dependent on tumor stage." (PMID 31992741, 2020). "NEAT1 has gained much NEAT1 attention due to its critical roles in maintenance of nuclear bodies, chromatin remodeling, gene expression regulation, and tumor progression in different cancers." (PMID 33221742, 2020). "The dysregulation of lncRNA NEAT1 exerts its oncogenic functions in the majority of human cancers." (PMID 32151082, 2020). "A variety of lncRNAs have been reported to regulate Akt signaling, and NEAT1 could modulate Akt signaling pathway in several cancers." (PMID 32268876, 2020). "LncRNA NEAT1 was manifested to participate in different biological processes of cancers." (PMID 33336058, 2020). "An interaction between NEAT1 and miR-129-5p has been reported in different types of cancer." (PMID 33574830, 2020). "NEAT1 has been reported to be involved in the development of many cancers." (PMID 33292252, 2020). "In the previous section, the established participation of paraspeckles in cancer was demonstrated using the CML context, where BCR–ABL, the main cause of a vast majority of CMLs, tends to activate c-Myc, which then represses NEAT1, which in turn prevents paraspeckle formation." (PMID 33143162, 2020). "LncRNA NEAT1 has been identified as a tumour driver in many human cancers." (PMID 32206038, 2020).
cancer (continued). "Moreover, NEAT1 increases MAPK pathway activity via sponging let-7a in cancer cells, resulting in increased phosphorylation of ERK1/2 and p38." (PMID 33298086, 2020). "Hence, targeting molecules specific to NEAT1/miR-129/Bcl-2 inside tumor cells can be a novel potential cancer treatment compared to conventional chemotherapy." (PMID 32692721, 2020). "It has been demonstrated that NEAT1 can target miRs to regulate cancer proliferation and migration." (PMID 32664703, 2020). "A number of evidences showed that NEAT1 has an important role in cancer chemoresistance." (PMID 32760219, 2020). "Finally, NEAT1 has been reported to regulate many cancer-related microRNAs whose targets mRNAs are involved in cell proliferation, migration, invasion, metastasis, EMT, stem cell-like phenotype, chemoresistance and radioresistance." (PMID 33138914, 2020). "This review will thus cover the range of effects by which NEAT1 interacts with cancer progression in order to describe the various roles of NEAT1 in chemoresistance, as well as to identify drug targets that protein research alone could not provide." (PMID 33143162, 2020). "The role of NEAT1 in cancer radioresistance may also involve other cellular proteins through the direct interaction or its ceRNA activity." (PMID 32922184, 2020). "In addition to extending the function of NEAT1 in tumor development, our study deepens the understanding of the impact of lncRNAs in the angiogenesis of cancer." (PMID 33680941, 2020). "Notably, NEAT1 deregulation has been reported in various types of cancers with important implications in the regulation of apoptotic cell death, cell growth, proliferation, invasion and metastasis, thus suggesting its possible role as a therapeutic target." (PMID 32630183, 2020). "Further research into the role of NEAT1 isoforms in the immune system will be required and could potentially reveal further insights into how the immune system combats cancer." (PMID 33143162, 2020). "Moreover, it has been demonstrated that NEAT1 is not only enriched in the nuclear but also found in the cytoplasm in cancer cells." (PMID 33298086, 2020). "Emerging evidence has shown that NEAT1 could exert carcinogenic activity in human cancers by acting as ceRNAs of several miRNAs, such as miR-21 and miR-1224." (PMID 32336952, 2020). "However, NEAT1 positively regulates downstream oncogenes expression mainly via acting as a ceRNA in cancers." (PMID 33298086, 2020). "NEAT1 levels (without distinguishing between isoforms) are also increased in the blood of cancer patients and this has been linked to increased NEAT1 levels in immune cells especially neutrophils." (PMID 33143162, 2020). "This oncogenic role of NEAT1 in cancers suggests that it may be a promising biomarker and also a candidate therapeutic target pending the completion of further studies into the underlying mechanisms." (PMID 32140098, 2020). "Additional inclusion of somatic mutation data from tumor genomics or evidence from transposon-mutagenesis screens in mice may pinpoint cancer-driver lncRNAs, including e.g., NEAT1." (PMID 33329688, 2020). "As an oncogenic lncRNA in several cancers, NEAT1 was also revealed to be overexpressed in AAA." (PMID 31868202, 2020). "LncRNA NEAT1, a scaffold factor, has been investigated to take part in diverse cancer progression." (PMID 33281873, 2020). "NEAT1, for instance, have been reported to regulate miRNAs activity in different kinds of cancer." (PMID 31481527, 2019). "Also, in NPC NEAT1 is differentially expressed and its expression influences cancer cell characteristics." (PMID 30430751, 2019).
cancer (continued). "If this is the way of ceRNA function of NEAT1 or if there is another explanation of the observed processes, then it still needs to be further investigated, but there are too many reports denying a role of NEAT1 in cancer." (PMID 30430751, 2019). "NEAT1 has been confirmed to be a crucial oncogene in multiple types of cancer." (PMID 31850199, 2019). "The medium value of NEAT1 expression in cancer tissues was determined as cut-off value." (PMID 31481527, 2019). "Furthermore, low NEAT1 expression was correlated with a poor prognosis in patients with certain types of cancers." (PMID 31186635, 2019). "As many authors conclude high levels of NEAT1 in cancer patients could serve as a useful prognostic biomarker." (PMID 30430751, 2019). "Our data highlighted the roles of NEAT1 chemoresistance and cancer stemness, suggesting that it could be used as a new clinical therapeutic target for treating TNBC patients especially those with drug resistance." (PMID 30894512, 2019). "In the HER2+ type, NEAT1 competes with LDHA regulating glycolytic processes within cancer cells." (PMID 30430751, 2019). "More than half of the NEAT1 studies in cancer have been published within the last 2 years." (PMID 30430751, 2019). "That's might be the reason why knockdown of NEAT1 or increase of miR‐193a‐3p could impede cancer progression in colorectal carcinogenesis and offer genetic evidence that NEAT1 is one of the critical regulators to control oncogene KRAS." (PMID 30575330, 2019). "Importantly, shNEAT1 reduced stem cell populations such as CD44+/CD24−, ALDH+, and SOX2+, implicating that NEAT1 was closely related to cancer stemness in TNBC." (PMID 30894512, 2019). "Despite the fact that there are reports on NEAT1 influencing disease progression by sponging miRNAs, the described paraspeckle-mediated effects on the transcriptional regulation seem to be of greater significance in the context of non-cancerous diseases." (PMID 30717168, 2019). "Recently, many papers have been reporting roles of lncRNA NEAT1 in cancer." (PMID 31186635, 2019). "NEAT1 has been reported to regulate miRNAs activity in different kinds of cancer." (PMID 31481527, 2019). "Thus, a simple comparison of NEAT1 expression between cancer and normal tissues seems to be insufficient to define NEAT1 roles in cancer." (PMID 31186635, 2019). "Numerous studies have shown that NEAT1, a lncRNA, is aberrantly expression in various cancers." (PMID 30346062, 2019). "LncRNA NEAT1 was found to function as an oncogene in different kinds of cancer." (PMID 31481527, 2019). "In this section, the involvement of NEAT1 in cancer biology will be discussed." (PMID 30430751, 2019). "NEAT1 is a key regulator of cancer initiation and progression." (PMID 30374364, 2018). "As shown by real-time PCR, NEAT1 expression was dramatically increased in cancer tissue specimens compared to normal control; further analysis indicated that higher NEAT1 expression was more commonly observed in specimens in advanced TNM stages and with lymph node metastasis." (PMID 29788922, 2018). "The effects of NEAT1 in human cancers have been thoroughly studied." (PMID 30053878, 2018). "So, generally, NEAT1 could regulate cancer progression by interrupt the crosstalk between miRNA and miRNA’s target mRNA." (PMID 30053878, 2018). "Taken together, NEAT1 has the potential to provide a new biomarker for the diagnosis and monitoring of cancers and will need to be taken into consideration in the development of NEAT1-targeting therapeutics (possibly in combination with chemotherapy and radiotherapy)." (PMID 30374364, 2018). "The presence of copy number gain in NEAT1 gene might provide a possible explanation for high NEAT1 expression in these cancers." (PMID 30374364, 2018).
cancer (continued). "Because cell invasion is an important aspect of cancer progression that involves the migration of tumor cells into contiguous tissues and the dissolution of extracellular matrix proteins, we evaluated the effects of NEAT1 on cell migration and invasion." (PMID 30154460, 2018). "Studies have demonstrated that LncRNA NEAT1 promotes cancer progression." (PMID 30459529, 2018). "In breast cancer, NEAT1 interacts with miR-101 to modulate cancer cell proliferation through EZH2." (PMID 29788922, 2018). "Taken together, NEAT1 could play a critical role in human cancers by inhibiting the effects of miRNAs." (PMID 29515109, 2018). "Induction of NEAT1 has been found to promote survival and proliferation of cancer cells." (PMID 29371689, 2018). "Moreover, MALAT1, another noticeable lncRNA in cancer, is tightly co-expressed with NEAT1 in both pRCC and ccRCC (Spearman’s correlation; 0.79 and 0.87 respectively)." (PMID 28358873, 2017). "Aberrant NEAT1 expression has been has been observed in several human cancers." (PMID 28968960, 2017). "Furthermore, the relationship between NEAT1 expression and a variety of cancer patients’ clinicopathological parameters were reported in previous studies." (PMID 28507281, 2017). "Likewise, NEAT1, as a novel lncRNA, has been recently found to be up-regulated in several cancers, contributing to tumor proliferation, apoptosis, metastasis and survival." (PMID 29163187, 2017). "NEAT1, a novel lncRNA, is potentially an important regulator in several kinds of cancers." (PMID 28938549, 2017). "Further subgroup analysis for OS showed that increased NEAT1 in cancer patients may be a reliable prognostic factor for hepato-gastroenterol cancers." (PMID 27926523, 2017). "Previous studies have proposed that NEAT1 could be a possible prognostic biomarker in cancer patients." (PMID 28118609, 2017). "This meta-analysis showed that NEAT1 expression may be a useful biomarker for predicting a poor prognosis in patients with cancer." (PMID 28507281, 2017). "Next, we evaluated the contribution of NEAT-1 on cancer cell phenotype." (PMID 28122578, 2017). "The last-mentioned study together with our results revealed a potential role of NEAT1 in maintaining stemness properties and suggested that Oct4-mediated NEAT1 upregulation may play critical roles in embryonic or cancer stemness maintenance." (PMID 28615056, 2017). "Overall, the pooled HRs revealed that NEAT1 expression might be served as a prognostic biomarker in various types of cancers." (PMID 29026116, 2017). "NEAT1 has also been found to increase the survival of cancer cells, and may thus benefit KSHV infection by preventing the death of KSHV-infected cells." (PMID 28046107, 2017). "In the present study, relevant publications were collected to investigate whether the increased expression of NEAT1 could be served as a potential biomarker for prognosis in cancer patients." (PMID 27926523, 2017). "Another noncoding hotpot was in NEAT1, a long noncoding RNA that has been speculated to involve in cancer." (PMID 28358873, 2017). "Eventually, they concluded that NEAT1 may serve as a molecular marker and a prognostic factor for patients with various cancers." (PMID 29163187, 2017). "NEAT1 has been reported to be involved in the pathogenesis of multiple types of cancer (7, –, 9)." (PMID 28202761, 2017). "However, our result derived from six microarray and RNA-seq datasets with 477 cancer patients and 344 normal controls showed that NEAT1 was down-regulated in ESCA tissues." (PMID 28118609, 2017). "Furthermore, many other established, cancer-linked lncRNAs, including HOTAIR, MALAT-1, NEAT-1, and UCA-1, were found to be either extremely lowly expressed (mean and median cpm < 1) or insufficiently dysregulated in HNSCCs." (PMID 27323410, 2016).